ZFP36L1 (ZFP36 like 1 zinc finger CCCH-type)
Description:
Zinc-finger RNA-binding protein that destabilizes several cytoplasmic AU-rich element (ARE)-containing mRNA transcripts by promoting their poly(A) tail removal or deadenylation, and hence provide a mechanism for attenuating protein synthesis. Acts as a 3'-untranslated region (UTR) ARE mRNA-binding adapter protein to communicate signaling events to the mRNA decay machinery. Functions by recruiting the CCR4-NOT deadenylase complex and components of the cytoplasmic RNA decay machinery to the bound ARE-containing mRNAs, and hence promotes ARE-mediated mRNA deadenylation and decay processes. Also induces the degradation of ARE-containing mRNAs even in absence of poly(A) tail (By similarity). Binds to 3'-UTR ARE of numerous mRNAs. Positively regulates early adipogenesis by promoting ARE-mediated mRNA decay of immediate early genes (IEGs) (By similarity). Promotes ARE-mediated mRNA decay of mineralocorticoid receptor NR3C2 mRNA in response to hypertonic stress. Negatively regulates hematopoietic/erythroid cell differentiation by promoting ARE-mediated mRNA decay of the transcription factor STAT5B mRNA. Positively regulates monocyte/macrophage cell differentiation by promoting ARE-mediated mRNA decay of the cyclin-dependent kinase CDK6 mRNA. Promotes degradation of ARE-containing pluripotency-associated mRNAs in embryonic stem cells (ESCs), such as NANOG, through a fibroblast growth factor (FGF)-induced MAPK-dependent signaling pathway, and hence attenuates ESC self-renewal and positively regulates mesendoderm differentiation (By similarity). May play a role in mediating pro-apoptotic effects in malignant B-cells by promoting ARE-mediated mRNA decay of BCL2 mRNA. In association with ZFP36L2 maintains quiescence on developing B lymphocytes by promoting ARE-mediated decay of several mRNAs encoding cell cycle regulators that help B cells progress through the cell cycle, and hence ensuring accurate variable-diversity-joining (VDJ) recombination and functional immune cell formation (By similarity). Together with ZFP36L2 is also necessary for thymocyte development and prevention of T-cell acute lymphoblastic leukemia (T-ALL) transformation by promoting ARE-mediated mRNA decay of the oncogenic transcription factor NOTCH1 mRNA (By similarity). Participates in the delivery of target ARE-mRNAs to processing bodies (PBs). In addition to its cytosolic mRNA-decay function, plays a role in the regulation of nuclear mRNA 3'-end processing; modulates mRNA 3'-end maturation efficiency of the DLL4 mRNA through binding with an ARE embedded in a weak noncanonical polyadenylation (poly(A)) signal in endothelial cells. Also involved in the regulation of stress granule (SG) and P-body (PB) formation and fusion. Plays a role in vasculogenesis and endocardial development (By similarity). Plays a role in the regulation of keratinocyte proliferation, differentiation and apoptosis. Plays a role in myoblast cell differentiation (By similarity).
Synonyms: ERF-1; BERG36; BRF1; ERF1; RNF162B; TIS11B; cMG1
Tractability: PROTAC: UniProt records ubiquitination sites on it; ubiquitination databases record sites on it.
Gene: Protein-coding gene on chromosome 14 (68,787,655 to 68,796,253, reverse strand). Ensembl gene ENSG00000185650.
Subcellular location: Nucleus; Cytoplasm; Cytoplasmic granule; Cytoplasm, P-body
Pathways (Reactome):
Metabolism of RNA: Butyrate Response Factor 1 (BRF1) binds and destabilizes mRNA
Gene Ontology:
Molecular function: 14-3-3 protein binding; mRNA 3'-UTR AU-rich region binding; mRNA binding; protein binding; RNA binding; mRNA regulatory element binding translation repressor activity; protein-RNA sequence-specific adaptor activity; metal ion binding
Biological process: 3'-UTR-mediated mRNA destabilization; cellular response to cAMP; cellular response to epidermal growth factor stimulus; cellular response to glucocorticoid stimulus; cellular response to hypoxia; cellular response to insulin stimulus; cellular response to peptide hormone stimulus; cellular response to transforming growth factor beta stimulus; cellular response to tumor necrosis factor; ERK1 and ERK2 cascade; MAPK cascade; mRNA transport; negative regulation of erythrocyte differentiation; phosphatidylinositol 3-kinase/protein kinase B signal transduction; positive regulation of intracellular mRNA localization; positive regulation of monocyte differentiation; regulation of gene expression; regulation of keratinocyte apoptotic process; regulation of keratinocyte differentiation; regulation of keratinocyte proliferation; regulation of mRNA 3'-end processing; regulation of mRNA stability; response to wounding; cellular response to fibroblast growth factor stimulus; cellular response to raffinose; and 13 more
Cellular component: cytoplasm; nucleus; P-body; ribonucleoprotein complex; cytosol
Genetic constraint (gnomAD): Loss-of-function variants: 4 observed, 17.07 expected, observed/expected ratio (o/e) 0.23, 90% interval 0.11 to 0.54. The upper end of that interval is the gene's LOEUF score, 0.54, which puts it in group 2 of 6, group 1 being the genes least tolerant of losing a copy. Missense variants: 311 observed, 464.26 expected, observed/expected ratio (o/e) 0.67, 90% interval 0.61 to 0.74. Synonymous variants: 220 observed, 198.72 expected, observed/expected ratio (o/e) 1.11, 90% interval 0.99 to 1.24.
Homologues: Orthologues: chimpanzee ZFP36L1 (99% identical), guinea pig ZFP36L1 (99% identical), mouse Zfp36l1 (99% identical), rat Zfp36l1 (99% identical), dog ZFP36L1 (98% identical), pig ZFP36L1 (95% identical), macaque ZFP36L1 (94% identical), tropical clawed frog zfp36l1 (73% identical), zebrafish zfp36l1a (66% identical), zebrafish zfp36l1b (63% identical), Caenorhabditis elegans ccch-1 (31% identical), Caenorhabditis elegans gla-3 (23% identical), and 17 more. Paralogues in human: ZFP36L2 (58% identical), ZFP36 (31% identical).
Diseases named in the same sentence as ZFP36L1 in open-access papers:
ZFP36L1 is named in the same sentence as 75 diseases in open-access papers, as found by Europe PMC text mining. Sharing a sentence is not in itself a finding about the gene and the disease. The quoted sentences say what the papers report.
breast carcinoma (7 papers, 2009 to 2024). "Genome-wide sequencing studies that identified ZFP36L1 as a driver gene in breast cancer and multiple myeloma, identifying inactivating mutations in the ZFP36L1 gene, provided more recent evidence supporting this hypothesis." (PMID 35008519, 2021). "Functionally, silencing ZFP36L1 enhanced tumor cell growth while overexpression of ZFP36L1 suppressed cell proliferation and migration in bladder and breast cancer cell lines." (PMID 32545247, 2020). "Significant overexpression of transcript Zfp36l1 was found in lymph node and breast carcinomas, and increased Fabp5 expression induces metastasis in human prostate carcinomas." (PMID 19190631, 2009). "Furthermore, these authors found that ZFP36L1 is epigenetically silenced through hypermethylation of the second exon and is downregulated in several patient cohorts of bladder and breast cancers." (PMID 32545247, 2020). "Forced expression of ZFP36L1 inhibited cell proliferation in bladder and breast cancer cells." (PMID 31999936, 2020). "Interestingly, ZFP36L1 was upregulated only in lymph node positive primary breast cancer, indicating that patterns of gene expression in primary tumors at the time of surgical removal could discriminate those that have lymph node metastasis." (PMID 32545247, 2020). "Our analysis revealed that the five unique hub genes (PPARG, HIPK2, ZFP36L1, HMGB2 and ALDH1A3) may constitute a gene expression signature specifying a therapeutic response of ERβ1-expressing ERα-positive breast cancer cells to treatment with OHT+ATRA." (PMID 36835157, 2023). "Similar to TTP, ZFP36L1 phosphorylation and inactivation by the p38–MK2 axis has been shown to stabilize Nanog and Klf4 in triple-negative breast cancer cells, resulting in breast cancer stem cell phenotype, a feature of chemotherapy-resistance in triple-negative breast cancer." (PMID 32545247, 2020).
acute lymphoblastic leukemia (5 papers, 2016 to 2022). Leukemia with an acute onset, characterized by the presence of lymphoblasts in the bone marrow and the peripheral blood. "Intriguingly, mice carrying double-deficiency of Zfp36l1 and Zfp36l2 in T-cell lineage results in the arrest of thymopoiesis at the double-negative stage and develop T cell acute lymphoblastic leukemia (T-ALL) due to aberrant activation of Notch signaling." (PMID 32655569, 2020). "Similarly, mice deficient for ZFP36L1 and ZFP36L2 displayed altered T cell development and readily succumbed to CD8+ T cell acute lymphoblastic leukemia." (PMID 27690235, 2016). "Importantly, double-deficiency of ZFP36L1 and ZFP36L2 in T-cell lineage in mice causes the arrest of thymopoiesis at the double-negative stage and develops T cell acute lymphoblastic leukemia (T-ALL) due to aberrant activation of Notch signaling." (PMID 34276705, 2021).
asthma (4 papers, 2021 to 2023). "Restoring ZFP36L1 and ZFP36L2 levels in primary bronchial epithelial cells from patients with severe asthma led to decreased expression of mRNAs encoding pro-inflammatory factors." (PMID 37928904, 2023). "Our data on murine models of acute and chronic asthma-like inflammation showed decreased of Zfp36l1 mRNA in the lung of chronic asthma-like inflammation (akin to human severe asthma), although these data correspond to whole lung." (PMID 37928904, 2023). "Analysis of the positively stained airway epithelial cells showed that patients with mild asthma had increased staining of ZFP36L1 in epithelial cells as compared with healthy controls and severe asthma." (PMID 37928904, 2023). "We also found decreased of Zfp36l1 and Zfp36l2 mRNA in chronic asthma-like inflammation (akin to human severe asthma) in mice." (PMID 37928904, 2023). "Patients with severe asthma showed low ZFP36L1 staining, significantly decreased as compared with mild but not healthy controls." (PMID 37928904, 2023). "In asthma samples, ZFP36L1 mRNA was decreased in mucous ciliated cells while it appeared to increase in ionocytes, ciliated and basal cycling cells." (PMID 37928904, 2023). "Zfp36l1/l2 nuclear localization was increased in the airways of mice with asthma-like characteristics." (PMID 37928904, 2023). "In bronchial biopsies, we observed a trend towards increased nuclear localization for ZFP36L2 in patients with severe asthma while ZFP36L1 appeared more localised in the cytosol." (PMID 37928904, 2023). "Immunostaining of human bronchial biopsies showed that airway epithelial cell staining of ZFP36L1 was decreased in severe asthma as compared with mild, while ZFP36L2 was upregulated." (PMID 37928904, 2023). "We assessed the lung mRNA expression and cellular localization of Zfp36l1 and Zfp36l2 in precision cut lung slices in murine asthma models." (PMID 37928904, 2023). "Discussion: We propose that the dysregulation of ZFP36L1/L2 levels as well as their subcellular mislocalization contributes to changes in mRNA expression and cytoplasmic fate in asthma." (PMID 37928904, 2023). "On the other hand, the expression of ZFP36L1 in bronchoalveolar lavage cells is higher in patients with steroid-resistant asthma than that in patients with steroid-sensitive asthma." (PMID 34276705, 2021). "Zfp36l1 was downregulated in the lung of a mouse model of asthma, and immunostaining of ex vivo lung slices with a dual antibody demonstrated that Zfp36l1/l2 nuclear localization was increased in the airway epithelium of an acute asthma mouse model, which was further enhanced in a chronic model." (PMID 37928904, 2023). "The tristetraprolin (TTP) family of RBPs, consisting of ZFP36, ZFP36L1 and ZFP36L2 in humans, has been implicated in the regulation of immune responses, but little is known about their role in epithelium or asthma." (PMID 37928904, 2023). "In summary, our analysis inferred that ZFP36L1 and ZFP36L2 encoding mRNAs are present in distinct airway epithelial cells and that ZFP36L2 preferentially targets mRNAs that are bound to polyribosomes in bronchial epithelial cells from patients with severe asthma." (PMID 37928904, 2023). "We further explored the potential role of ZFP36L1 and ZFP36L2 in bronchial epithelial cells in asthma." (PMID 37928904, 2023). "Restoring the levels of ZFP36L1 and ZFP36L2 in primary bronchial epithelial cells from patients with severe asthma decreased the mRNA expression of IL6, IL8 and CSF2." (PMID 37928904, 2023). "Together, our data strongly suggest that ZFP36L1 and ZFP36L2 drive changes in gene expression in primary epithelial cells in asthma." (PMID 37928904, 2023). "ZFP36L1 and ZFP36L2 alter post-transcriptional gene expression in bronchial epithelial cells in severe asthma, granting further investigation into their role in chronic airway inflammation." (PMID 37928904, 2023).
asthma (continued). "Modulating ZFP36L1 and ZFP36L2 in primary bronchial epithelial cells from patients with asthma decreased the expression of known pro-inflammatory mediators." (PMID 37928904, 2023). "We observed significantly decreased binding of ZFP36L1 and ZFP36L2 mRNAs to polyribosomes in primary bronchial epithelial cells from severe asthma patients compared to age- and sex-matched healthy controls (both p < 0.05)." (PMID 37928904, 2023). "Our data demonstrate that ZFP36L1 and ZFP36L2 levels and subcellular localization are dysregulated in primary samples from both human and murine-like asthma." (PMID 37928904, 2023). "To determine the effects of restoring ZFP36L1 and ZFP36L2 levels, we employed a vector to overexpress Zfp36l1 and siRNAs to deplete ZFP36L2 in primary bronchial epithelial cells from patients with severe asthma." (PMID 37928904, 2023). "Taken together, our data show that ZFP36L1 and ZFP36L2 are expressed in airway epithelial cells and that their levels and subcellular localization are modified in asthma, in a severity-dependent manner." (PMID 37928904, 2023). "ZFP36L1 and ZFP36L2 mRNAs appeared differentially expressed in individual airway epithelial cell types, with these expression patterns varying between health and asthma." (PMID 37928904, 2023). "Together, these data point towards chronic inflammation driving changes in ZFP36L1 expression in asthma, while glucocorticoids may be the main drivers of ZFP36L2 protein expression in severe asthma." (PMID 37928904, 2023). "Notably, nuclear accumulation of Zfp36l1/l2 at 5-week HDM treatment was even more dramatic, demonstrating a positive correlation between nuclear Zfp36l1/l2 and asthma severity." (PMID 37928904, 2023). "Finally, we determined the expression in airway epithelium of ZFP36L1 and ZFP36L2 in human bronchial biopsies and performed rescue experiments in primary bronchial epithelium from patients with severe asthma." (PMID 37928904, 2023). "After having analysed the levels of ZFP36L1 and ZFP36L2 in omics mRNA datasets and inferring their role in ARE regulation and epithelial cell biology, we interrogated their expression levels in an in vivo model of asthma." (PMID 37928904, 2023). "Dysregulation of ZFP36L1/L2 in severe asthma epithelium was found to contribute to glucocorticoid non-responsiveness as well as epithelial barrier disruption." (PMID 35606385, 2022). "At the protein level, in human bronchial biopsies, ZFP36L1 showed an increase in expression in mild patients, i.e., not taking glucocorticoids, as compared to healthy controls, and a decrease in patients with severe asthma." (PMID 37928904, 2023). "To further investigate the dysregulation of both ZFP36L1 and ZFP36L2 mRNA levels in human and mouse asthma we performed immunostaining of ZFP36L1 and ZFP36L2 in bronchial biopsies from patients with different asthma severities and non-asthma controls." (PMID 37928904, 2023).
bladder cancer (4 papers, 2016 to 2024). "It is still pending to distinguish the high expression of ZFP36L1 is a cause or effect of the EMT of bladder cancer cells in vivo." (PMID 35359594, 2022). "The frequency of ZFP36 gene family mutations ranged between 9.1 and 10%, among the three bladder carcinoma cohorts; notably, mutations of ZFP36L1 and ZFP36L2 were mutually co-occurring (P = 0.02; FDR = 0.06)." (PMID 33397444, 2021). "Strikingly, ZFP36L1 mutations were consistently altered in three independent studies exploring the genetic landscape of bladder carcinomas (TCGA, DFCI, and BGI), with frequencies ranging from 6 to 8.5%." (PMID 33397444, 2021). "This study reveals a potential invasion promoting role of ZFP36L1 in bladder cancer the first time, which may explain the association of ZFP36L1 expression with the prognosis of BC patients somehow." (PMID 35359594, 2022). "Moreover, GSEA based on the bladder cancer RNA-Seq data identified 5 cancer metastasis associated pathways may be activated by the high level of ZFP36L1." (PMID 35359594, 2022). "For example, ZFP36L1 decreases numerous oncogenic transcripts that are involved in the cell cycle and hypoxic signaling pathways in bladder cancer, leading to inhibition of hypoxic adaptation, metabolism, angiogenesis, and cell cycle progression." (PMID 37935976, 2024). "Overexpression of ZFP36L1 markedly repressed the proliferation of bladder cancer cells as shown in the colony formation assay." (PMID 35359594, 2022). "In the current study, we aimed to gain insight on the function of ZFP36L1 in bladder cancer and explore the correlation between ZFP36L1 expression and the prognosis of BC patients." (PMID 35359594, 2022). "To examine the metastasis related function of ZFP36L1 in MIBCs, we sought to assess the effect of ZFP36L1 on the invasion of bladder cancer cell lines established from MIBC in vitro." (PMID 35359594, 2022). "When we combined mutations of ZFP36L2 and ZFP36 to ZFP36L1, the frequency of ZFP36 gene family mutations reached 3% (n = 297) in all TCGA cohorts, with the highest frequencies observed in bladder cancers." (PMID 33397444, 2021). "To investigate the biological role of ZFP36L1, we performed loss-of-function experiments of ZFP36L1 using siRNA in the TCCSUP bladder cancer cell line." (PMID 33397444, 2021). "Reduced ZFP36L1 attenuated the invasiveness of bladder cancer cells." (PMID 35359594, 2022). "Although limitations of this study, including a lack of in vivo experiments evidence, suggest further research is expected, we believe the results above raise attention to the tumor progression regulating role of ZFP36L1 in bladder cancer which may need to be reconsidered more carefully." (PMID 35359594, 2022). "Functions of ZFP36L1 in MIBC were investigated further, and it was found that while ZFP36L1 suppressed the self-renewal of bladder cancer cells, it promoted the invasiveness of the cells markedly." (PMID 35359594, 2022).
leukemia (4 papers, 2014 to 2022). A malignant (clonal) hematologic disorder, involving hematopoietic stem cells and characterized by the presence of primitive or atypical myeloid or lymphoid cells in the bone marrow and the blood. "Functionally, ZFP36L1 expression induced apoptosis in leukemia cells, indicating a tumor-suppressor role of ZFP36L1 in myelofibrosis." (PMID 32545247, 2020). "Although the function of HuR has not been directly assessed in MLL-r leukemia, it has been shown to regulate and associate with other ARE RBPs that have been shown to be aberrantly expressed in MLL-r leukemia such as EIF4E, NCL, and ZFP36L1." (PMID 36307883, 2022).